ZNF562 (zinc finger protein 562)
Description:
May be involved in transcriptional regulation.
Synonyms: FLJ20079
Tractability: PROTAC: ubiquitination databases record sites on it.
Gene: Protein-coding gene on chromosome 19 (9,641,807 to 9,675,100, reverse strand). Ensembl gene ENSG00000171466.
Subcellular location: Nucleus
Subcellular location (Human Protein Atlas): Nucleoplasm
Pathways (Reactome):
Gene expression (Transcription): Generic Transcription Pathway
Gene Ontology:
Molecular function: DNA-binding transcription factor activity, RNA polymerase II-specific; RNA polymerase II cis-regulatory region sequence-specific DNA binding; sequence-specific double-stranded DNA binding
Biological process: regulation of DNA-templated transcription; regulation of transcription by RNA polymerase II
Cellular component: nucleus
Genetic constraint (gnomAD): Loss-of-function variants: 13 observed, 18.45 expected, observed/expected ratio (o/e) 0.7, 90% interval 0.46 to 1.12. The upper end of that interval is the gene's LOEUF score, 1.12, which puts it in group 4 of 6, group 1 being the genes least tolerant of losing a copy. Missense variants: 481 observed, 502.9 expected, observed/expected ratio (o/e) 0.96, 90% interval 0.89 to 1.03. Synonymous variants: 163 observed, 168.28 expected, observed/expected ratio (o/e) 0.97, 90% interval 0.85 to 1.1.
Homologues: Orthologues: chimpanzee ZNF562 (96% identical), tropical clawed frog zfx (21% identical), zebrafish zfx (21% identical), mouse Zfy1 (20% identical), rat Zfy1 (20% identical), mouse Zfy2 (19% identical). Paralogues in human: ZNF561 (84% identical), ZNF256 (38% identical), ZNF304 (37% identical), ZNF549 (36% identical), ZNF570 (36% identical), ZNF583 (36% identical), ZNF480 (35% identical), ZNF792 (35% identical), ZNF773 (35% identical), ZNF419 (34% identical), ZNF551 (33% identical), ZNF79 (33% identical), and 26 more.
Diseases named in the same sentence as ZNF562 in open-access papers:
ZNF562 is named in the same sentence as 4 diseases in open-access papers, as found by Europe PMC text mining. Sharing a sentence is not in itself a finding about the gene and the disease.
ZNF562 shares sentences with these, for which no sentence is quoted: cancer (2 papers); breast carcinoma (1); ovarian carcinoma (1); tumor (1).